PPARG (peroxisome proliferator activated receptor gamma)
Diseases named in the same sentence as PPARG in open-access papers (continued):
Sharing a sentence is not in itself a finding about the gene and the disease.
preeclampsia (continued). "Nevertheless, several study groups did not detect differences between healthy and preeclamptic placentae, while some authors even suggested PPARγ up-regulation in preeclampsia." (PMID 36831316, 2023). "On the contrary, a significantly greater number of studies have investigated the role of PPARγ in preeclampsia, with the majority of these studies reporting a reduction in PPARγ in preeclampsia." (PMID 36831316, 2023). "Placental PPARγ is produced by trophoblasts and endometrial stromal cells and is known to be reduced in preeclampsia." (PMID 34830351, 2021). "It has also been suggested that PPARγ plays a role in elevating blood pressure, proteinuria, endothelial dysfunction, and platelet aggregation, i.e., key features of preeclampsia in rats." (PMID 34685423, 2021). "This study aims to investigate the expression of PPARγ in early onset preeclampsia (EOPE), late onset preeclampsia (LOPE), and normal pregnancy." (PMID 32216842, 2020). "Peroxisome proliferator-activated receptor γ (PPARγ) has been shown to be a therapeutic target for preeclampsia (PE)." (PMID 28933788, 2017). "Decreased peroxisome proliferator-activated receptor gamma (PPARγ) activity is thought to have a major role in preeclampsia through abnormal placental development." (PMID 23888144, 2013). "The potential involvement of PPARγ on preeclampsia is suggested by the fact that this pathology isassociated with an increased peroxidation in trophoblasts." (PMID 18288292, 2008). "The relationship between the PPARγ and preeclampsia has been widely reported." (PMID 34685423, 2021). "Interestingly, PPARγ has a critical role in regulating inflammatory cytokines including TNF-α and IL-6, which were linked to preterm labor, miscarriage, and preeclampsia." (PMID 35011648, 2021). "Recent studies in rat models also suggest an important role for PPARγ in preeclampsia." (PMID 23888144, 2013). "Perhaps, at the level of clinician actual knowledge, PPARγ and its ligands could be used ina first time, only as good early marker candidates for the diagnosis ofpregnancy pathologies like, for example, preeclampsia." (PMID 18288292, 2008). "Certain research groups could, however, not detect any correlation between PPARγ (polymorphism) and the occurrence of preeclampsia, with the clinical course of preeclampsia not differing among PPARγ genotypes." (PMID 36831316, 2023). "The transition to upregulated PPAR signaling in later gestation in PIH cases observed here may reflect pathway cross talk or compensatory processes that ensure offspring survival, as PPARγ is expected to be consistently lower in serum from mothers with preeclampsia." (PMID 37184228, 2023). "The search terms used were “peroxisome proliferator-activated receptor-gamma”, “PPARγ”, “PPAR gamma”, “gestational diabetes mellitus” and “preeclampsia”." (PMID 37299422, 2023). "Furthermore, we aimed to characterize a possible interaction between PPARγ and H3K4me3 (trimethylated lysine 4 of the histone H3), respectively H3K9ac (acetylated lysine 9 of the histone H3), to illuminate the role of histone modifications in a defective trophoblast invasion in preeclampsia (PE)." (PMID 34830351, 2021). "Our data uncover uterine vascular dysfunction as an early mechanism that may lead to placental hypoperfusion and intrauterine growth restriction in human pregnancies associated with negative mutations in PPARγ or reduced levels of circulating PPARγ activators, such as that seen in preeclampsia." (PMID 23888144, 2013). "Furthermore, therapeutic interventions targeting factors such as peroxisome proliferator-activated receptor gamma (PPAR-γ) and endothelin receptors show potential in mitigating preeclampsia-related complications." (PMID 38674114, 2024). "In addition to its effects in preeclampsia, KFL8 also plays a role in 3T3-L1 adipocyte differentiation by acting as an upstream regulator of peroxisome proliferator-activated receptor gamma (PPARγ)." (PMID 25705690, 2015).
preeclampsia (continued). "GCM-1 may be regulated by the transcription factor peroxisome proliferator-activated receptor-gamma (PPAR-γ); in mice, PPAR-γ promotes labyrinthine trophoblast differentiation via Gcm-1, and, as we previously demonstrated, PPAR-γ activation ameliorates disease features in rat model of preeclampsia." (PMID 24711815, 2014).
liver disease (27 papers, 2009 to 2025). "This study showed that rs225014 (DIO2), rs532446 (GADD45A), rs12031994 (AKT3), rs11119982 (ATF3), rs10865710 (PPARG) are associated with the increased risk of liver disease progression in chronic hepatitis b carriers." (PMID 37059745, 2023). "As a result, our study demonstrated that rs225014 (DIO2), rs532446 (GADD45A), rs12031994 (AKT3), rs11119982 (ATF3), rs10865710 (PPARG) might contribute to the increased risk of liver disease progression in chronic hepatitis b carriers." (PMID 37059745, 2023). "For instance, PPARγ, FXR, and LXR agonists have been linked to tumorigenesis in hormone-sensitive cancers and liver diseases." (PMID 40926269, 2025). "Identification of the role and regulatory mechanism of PPARγ in necroptosis extends our understanding of Nrf2 signaling in liver injury and offers additional potential targets for drug development in liver diseases." (PMID 41176603, 2025). "The exploration of natural PPARγ agonists has shown promising therapeutic efficacy in various liver diseases." (PMID 39161898, 2024). "Though PPARγ is a known regulator of fatty acid redistribution, its role in steatotic liver disease is controversial." (PMID 39796579, 2024). "Even though PPARγ is less abundant in the liver than PPARα, it is still crucial for liver function, and the DNA methylation state of the Pparγ gene has been identified as a marker of the progression of liver disease." (PMID 37190114, 2023). "Liver disease was phenotypically evaluated using histology and biochemical methods, and anti-inflammatory properties and peroxisome proliferator-activated receptor gamma activation by norUDCA were evaluated in cellular model systems." (PMID 37818230, 2023). "In multivariate analyses adopting a dominant model rs225014 TT (DIO2) and rs10865710 CC (PPARG) and portal hypertension remained an independent predictor of advanced fibrosis, whereas DIO2 rs225017 lost significance (p > 0.05)." (PMID 37059745, 2023). "Our findings also provide new insights into the mechanism by which PCB2 exerts its anti-pyroptotic effects and hepatic benefits through the activation of PPARγ, highlighting the beneficial effects of dietary procyanidins against hepatic diseases." (PMID 35565726, 2022). "Pretreatment with the PPARγ inhibitor GW9662 blocked JWH133-induced attenuation of portal hypertension and upregulation of HO-1." (PMID 34393784, 2021). "Both experimental and clinical research results have indicated PPARγ agonists from natural products play vital roles in their protective effects in liver diseases." (PMID 32031298, 2020). "An interesting question is the cellular source of the hypermethylated PPARγ DNA in plasma of liver disease patients." (PMID 27002005, 2017). "Additionally, adropin modulates lipid metabolism by regulating the expression of liver disease-related genes and peroxisome proliferator-activated receptor gamma (PPARγ), a key regulator of lipogenesis." (PMID 39906123, 2025). "The activation of both Nrf2 and PPARγ can ameliorate liver injury, as they play pivotal roles in liver disease progression by regulating the expression of genes involved in critical processes such as hepatic metabolism, energy homeostasis, and oxidative stress." (PMID 41176603, 2025). "The role of PPARγ may switch to protective during the later stages of liver disease as the overexpression of PPARγ in hepatic stellate cells (HSCs) protects against fibrosis." (PMID 40985048, 2025). "Importantly, in steatotic liver disease, supplementation of beneficial Lactoplantibacillus plantarum improves PPARγ expression within its transcriptional network when introduced in high-fat-diet-induced MASLD murine models." (PMID 39796579, 2024). "Therefore, our present review summarizes the latest research progress of PPARγ agonists from natural products in recent years and explores the application prospect of PPARγ natural agonists in the treatment of liver diseases." (PMID 32031298, 2020).
liver disease (continued). "Even, few reviews of the effects of PPARγ natural agonists in liver disease have been published." (PMID 32031298, 2020). "However, the limitation of this review is that there are few studies on the treatment of liver diseases with PPARγ natural agonists." (PMID 32031298, 2020). "Hence, irrespective of the cause of steatotic liver disease, progression to the advanced stage is associated with PPARγ promoter hypermethylation in DNA isolated from plasma and hepatocyte-enriched regenerative nodules." (PMID 27002005, 2017). "However, TSG’s hepatotoxic effects are manifested through the inhibition of PPARGC1A and PPARγ expression, thereby activating the NF-κB and STAT signaling pathways, commonly dysregulated in liver diseases and potentially leading to LI." (PMID 39963244, 2025). "This metabolic shift is mediated by epigenetic mechanisms that up-regulate genes involved in hepatic lipogenesis such as PPARγ, very low-density lipoprotein receptor (VLDLR), and CD36, contributing to the onset of steatotic liver disease and intensifying the effects of metabolic syndrome." (PMID 39796579, 2024). "The co-targets are closely related to liver diseases, and in the degree order, the top four included heat shock protein 90AA1 (HSP90AA1), peroxisome proliferator-activated receptor G (PPARG), heat shock protein 90AB1 (HSP90AB1), and signal transduction and transcriptional activator 1 (STAT1)." (PMID 33510287, 2021). "Therefore, considering the relevant traditional use of silymarin, as well as the existing potential to modulate liver disease by PPAR modulation, it was studied whether silymarin and its purified flavonolignan and flavonoid constituents were able to activate PPARγ." (PMID 27069281, 2016).
esophageal cancer (25 papers, 2005 to 2025). A primary or metastatic malignant neoplasm involving the esophagus. "Taken together, the gene expression of PPARγ is associated with the development and prognosis of esophageal cancer." (PMID 29483923, 2018). "The CRC formed by E74 like ETS transcription factor 3 (ELF3), KLF5, and GATA6 upregulates peroxisome proliferator-activated receptor gamma (PPARG) in esophageal cancer, leading to increased synthesis of fatty acids, phospholipids, and sphingolipids." (PMID 40032852, 2025). "In esophageal cancer cells, PPARG activation by rosiglitazone led to suppressed proliferation and induced apoptosis through the inhibition of the Toll-like receptor 4 (TLR4)-dependent MAPK pathway." (PMID 40564064, 2025). "In esophageal cancer cells, PPARG signaling activation inhibited proliferation and induced apoptosis by inhibiting TLR4-dependent MAPK signaling." (PMID 36114448, 2022). "Studies on esophageal cancer cells indicate that PPARg stimulation leads to a decrease in PCNA (proliferating cell nuclear antigen factor) expression, which indicates inhibition of DNA replication." (PMID 32850012, 2020). "Decreased levels of PPARG gene have been observed in patients with esophageal cancer that is correlated with poor prognosis in patients." (PMID 31263479, 2019). "Rosiglitazone activation of PPARγ suppressed proliferation and induced apoptosis of esophageal cancer cells by inhibiting TLR4-dependent MAPK pathway." (PMID 31011554, 2019). "Further studies in different experimental systems consistently demonstrated that PPARγ-Akt signaling pathway was regulated by α-Tocopherol and played a critical role during the entry stage of esophageal cancer." (PMID 29221176, 2017). "PPARG is reported to function as an oncogene in ESCC and the activation of PPARG suppresses cell proliferation and induces cell apoptosis of esophageal cancer cells by inhibiting the TLR‐4 dependent mitogen‐activated protein kinase pathway." (PMID 28904855, 2017). "In our study, we found that PPARγ agonist RGZ had an ability to inhibit proliferation of esophageal cancer cells in time- and dose-dependent manners." (PMID 27323819, 2016). "Collectively, these results indicate that PPARγ agonist inhibits TLR4 signaling in esophageal cancer cells." (PMID 27323819, 2016). "The role of PPARγ in the progression of esophageal cancer remains controversial: activation of PPARγ inhibits cell growth and induces apoptosis in vitro; however, PPARγ agonists promote tumor growth in xenografted mice." (PMID 27323819, 2016). "In summary, these results reveal that PPARγ activation inhibits the MAPK signaling pathway in esophageal cancer cells." (PMID 27323819, 2016). "The aim of the present study is to illuminate the signaling network which orchestrates the regulation of TLR4 and MAPK pathway by PPARγ activation in esophageal cancer cells." (PMID 27323819, 2016). "In general, our data suggested that activation of PPARγ suppressed proliferation and induced apoptosis of esophageal cancer cells by inhibiting TLR4-dependent MAPK pathway." (PMID 27323819, 2016). "Taken together, all these findings suggest that PPARγ is acting as a heterodimer with RXRα to suppress proliferation of esophageal cancer cells." (PMID 27323819, 2016). "In conclusion, our study demonstrated that PPARγ activation inhibited proliferation and induced apoptosis esophageal cancer cells in vitro." (PMID 27323819, 2016). "We deduced that PPARγ agonist RGZ inhibited progression of esophageal cancer cells via blocking TLR4 pathway in our system." (PMID 27323819, 2016). "Our data in this study showed that inactivation of MAPK inhibited viability and induced apoptosis of esophageal cancer cells by PPARγ agonist or siRNA targeting ERK, JNK, and p38, which are consistent with these results." (PMID 27323819, 2016).
esophageal cancer (continued). "In conclusion, our data suggested that activation of PPARγ suppressed proliferation and induced apoptosis of esophageal cancer cells by inhibiting TLR4-dependent MAPK pathway." (PMID 27323819, 2016). "Taken together, these data suggest that activation of PPARγ inhibits proliferation and induces apoptosis of esophageal cancer cells by inhibiting TLR4-dependent MAPK pathway." (PMID 27323819, 2016). "PPARγ suppresses the growth and invasion of human colon and gastric and esophageal carcinoma cells, and both PPARγ and PPARα have anti-inflammatory actions." (PMID 21318167, 2010). "The expression of PPARγ protein is decreased in oesophageal cancer tissues compared with normal oesophageal squamous epithelium." (PMID 15583697, 2005). "The results also suggest that PPARγ plays an important role in the invasion of cancer cells and may be a new target for the treatment of esophageal cancer." (PMID 36035171, 2022). "Finally, wikstrol A can induce apoptosis in esophageal carcinoma Eca-109 cells and block their cell cycle in the S phase by up-regulation of the peroxisome proliferator-activated receptor-gamma (PPARγ) expression." (PMID 36059675, 2022). "Taken together, our study suggested that α-Tocopherol may serve as a PPARγ agonist for the chemoprevention of esophageal cancer." (PMID 29221176, 2017). "Though some small molecule agonist of PPARγ has been shown to reduce the phosphorylation of Akt at Ser473 and exert therapeutic effects in esophageal cancer, the relation between PPARγ protein expression and prognosis in human ESCC still remains unclear." (PMID 29221176, 2017). "The results showed that RGZ suppressed proliferation and induced apoptosis of esophageal cancer cells, which could be partly restored by inactivation of PPARγ." (PMID 27323819, 2016). "The roles and mechanisms of PPARγ activation in esophageal cancer remain unclarified." (PMID 27323819, 2016). "EC109 and TE10 esophageal cancer cells were treated with 0, 10, 20 and 40 mM of PPARγ agonist rosiglitazone (RGZ) for 24, 48, and 72 h, and the cell viability and apoptosis were detected using methyl thiazolyl tetrazolium (MTT) assay and Flow cytometric (FCM) analysis, respectively." (PMID 27323819, 2016). "Therefore, the better understanding of the mechanisms by which PPARγ functions as a suppressor in esophageal cancer is beneficial to PPARγ agonist utilization for the treatment of esophageal cancer." (PMID 27323819, 2016). "Therefore, the role of PPARγ on esophageal cancer cells and the mechanisms in the response to PPARγ agonists in esophageal cancer cells remain to be further elucidated." (PMID 27323819, 2016). "Similarly, Hashimoto and colleagues used a combination of 9-cis RA and troglitazone in the same concentrations on the KYSE series of esophageal carcinoma cell lines that all express high levels of RXRα and variable (though present) levels of PPARγ." (PMID 19267912, 2009). "In addition to PPARγ, PPARδ could also act as an essential mediator for 83b1 to exert anti-cancer effects on human esophageal cancers by down-regulating cancer-related genes and molecules." (PMID 37025484, 2023). "PPARγ activation also inactivated the TLR4 and ERK, JNK, and p38 MAPK pathways in esophageal cancer cells." (PMID 27323819, 2016).
partial lipodystrophy (25 papers, 2006 to 2025). Loss and redistribution of subcutaneous and/or visceral adipose tissue from specific regions of the body. "Protein-truncating mutations in PPARG are rare but have been described previously in individuals with T2D and partial lipodystrophy." (PMID 29207974, 2017). "Partial lipodystrophy had also been observed in clinic patients with a heterozygous PPARγ mutation." (PMID 37235264, 2023). "Third, while the beneficial effect of thiazolidinediones, one of very few drugs that clearly improve insulin sensitivity, was recognized before the discovery of PPARG mutations in patients with partial lipodystrophy, this link attests to the potential for human genetics to inform drug discovery." (PMID 34875679, 2022). "But the anecdotal nature of the between-sex differences in phenotypic severity in PPARγ-deficiency and in partial lipodystrophy precludes speculation regarding potential mechanisms." (PMID 16412238, 2006). "Individuals reported in the studies included 90 with partial lipodystrophy (72 due to LMNA mutation and 15 due to PPARG mutation), 42 with generalized lipodystrophy (21 AGPAT2, 21 BSCL2, 2 LMNA), and 19 with IR due to INSR mutation(s)." (PMID 37794082, 2023). "Another study examined seven individuals with partial lipodystrophy, two of whom had LMNA and PPARG variants, four with unknown genetic causes, and one patient with generalized lipodystrophy." (PMID 38633761, 2024). "Finally, considering that only two cases of human partial lipodystrophy associated with antiphospholipid and anticardiolipin antibodies were reported, it is likely that specific PPARγ deletion at cellular level, rather than the lipoatrophy, is fundamental in favoring the autoimmune response." (PMID 28182703, 2017).